ACLY (ATP citrate lyase)
Diseases named in the same sentence as ACLY in open-access papers (continued):
Sharing a sentence is not in itself a finding about the gene and the disease.
gastric cancer (12 papers, 2020 to 2025). A primary or metastatic malignant neoplasm involving the stomach. "The upregulated expression and activity of ACLY have been reported in lung, prostate, bladder, breast, liver, colon, and gastric cancer, whereas the inhibition of ACLY suppresses the proliferation of tumor cells." (PMID 39551780, 2024). "Immunohistochemistry and molecular analyses confirmed high ACLY expression in gastric cancer tissues and cells." (PMID 41676025, 2024). "In gastric cancer, the enzymes catalyzing the de novo synthesis of FAs (e.g., ACLY, ACC, FASN, and SCDs) were significantly up-regulated." (PMID 35785165, 2022). "To study the role of ACLY in the lipid metabolism of GC cells, we designed to measure the changes of lipid content in gastric cancer cells with relative higher and lower ACLY expression." (PMID 36064336, 2022). "Citrate and inhibitors of ACLY can reduce its expression, thus protecting against gastric cancer cell progression." (PMID 32848739, 2020). "For instance, ATP citrate lyase and fatty acid synthase are often found overexpressed in gastric cancer tissues, where increased expression of these genes facilitates fatty acid synthesis, providing essential energy and structural support for tumor cell growth." (PMID 40978035, 2025). "In fatty acid anabolism, SREBP1, ACLY, ACSs, ACC, FASN, and SCD1 enhance the occurrence, progression, and metastasis of gastric cancer, and are expected to be potential prognostic markers." (PMID 35625633, 2022). "In addition, ACLY can be downregulated by miR-133b via PPARγ and lncRNA FLJ22763 in gastric cancer." (PMID 32848739, 2020).
steatosis (12 papers, 2011 to 2025). Increased lipid within the cytoplasm of cells. "Further analysis also revealed that the increased expression of USP22, PPARγ, ACC and ACLY were associated with steatosis in the HCC TMAs." (PMID 35449157, 2022). "The increased expression of PPAR γ, ATP citrate lyase (ACLY) and acetyl-CoA carboxylase (ACC) are associated with steatosis of HCC." (PMID 40351413, 2025). "In the present study, the molecular mechanism of ACLY expression in a cell model of steatosis has been reported." (PMID 32054087, 2020). "Although ACLY is well known for its metabolic function in suppressing fatty acid and cholesterol synthesis, we have demonstrated that hepatocyte-specific ACLY deletion not only suppresses intratumoural steatosis and proliferation but also enhances antitumour immunity." (PMID 40739358, 2025). "Blocking of miR-122 expression in obese mice models using the same technique resulted in repression of plasma cholesterol and improved liver tissue steatosis by repressing the gene expressions related to fatty acid synthesis such as FAS and ACLY." (PMID 36979705, 2023).
hyperlipidemia (11 papers, 2014 to 2025). "In liver and adipocytes, ACLY plays an important role linking glucose metabolism to lipogenesis and membrane formation and is associated with hyperlipidemia." (PMID 40499285, 2025). "Consistently, ISOGK treatment also significantly inhibits ACLY activity in vivo via measured enzymatic activity in the liver tissue of three hyperlipidemia model animals." (PMID 40225566, 2025). "Because the inhibition of ACLY (ACLYi) mitigates hyperlipidemia and fatty acid declines ACLY expression, the connection is unclear." (PMID 39861346, 2025). "This was further confirmed by an in silico molecular modelling study, where all of the tested compounds showed certain inhibitory potential towards human α-glucosidase (HAG) and ATP citrate lyase (ACL) that play a crucial role in the pathogenesis of hyperglycemia and hyperlipidemia." (PMID 36143486, 2022). "Interestingly, ACLY synthesizes lipids and creates hyperlipidemia." (PMID 39861346, 2025). "In addition, although the inhibition of ATP citrate lyase (ACLYi) attenuates hyperlipidemia, and ACLY acetylates the histones by epigenetic mechanisms, their role in heart failure and the epigenetic control of homocystinuria is unknown." (PMID 39727952, 2024). "One ACLY inhibitor (bempedoic acid) is currently approved to treat lipidemia in statin-intolerant patients, although the drug requires activation in the liver and so does not impact ACLY in other organs." (PMID 40499285, 2025).
osteosarcoma (11 papers, 2016 to 2025). A usually aggressive malignant bone-forming mesenchymal neoplasm, predominantly affecting adolescents and young adults. "For instance, lncRNA XIST in MSC-EVs can promote osteosarcoma growth and metastasis through the miR-655/ACLY signaling." (PMID 38697996, 2024). "The presence of lncRNA XIST in MSC-EVs promotes osteosarcoma growth and metastasis through the miR-655/ACLY signaling pathway." (PMID 38697996, 2024). "ACLY plays a role in promoting cancer in a variety of tumors, including osteosarcoma, and targeting ACLY is considered to be one of the important strategies for tumor prevention and treatment." (PMID 36309693, 2022). "After mutated at the putative miR-655 binding sites, the relative luciferase activity was restored, which indicated that BMSCs derived exosome XIST can promote the expression of ACLY in osteosarcoma cells by binding to miR-655." (PMID 36309693, 2022). "In-depth mechanism study showed that BMSCs derived exosomal XIST combined with miR-655 to increase the protein level of ACLY, which led to lipid deposition and activate β-catenin signal to promote the proliferation, migration and invasion of osteosarcoma cells." (PMID 36309693, 2022). "Finally, we analyzed the effect of BMSCs derived exosomal XIST on the biological function of osteosarcoma by enhancing ACLY expression in combination with miR-655." (PMID 36309693, 2022). "We found that BMSCs derived exosomal XIST combined with miR-655 could increase the expression level of ACLY and promote the proliferation, migration and invasion of osteosarcoma cells." (PMID 36309693, 2022). "In osteosarcoma, ACLY drives tumor growth and metastasis via the XIST/miR-655/ACLY axis, while miR-22 downregulates ACLY to inhibit lipogenesis, highlighting its potential as a therapeutic target." (PMID 40370434, 2025). "BMSCs derived exosomal XIST binds miR-655 to promote ACLY expression, and then enhances β-catenin signal activity, which is another mechanism of XIST to accelerate the growth and metastasis of osteosarcoma." (PMID 36309693, 2022). "It was found that BMSCs derived exosomes could promote the expression of ACLY in osteosarcoma cells, inhibition of XIST expression reduces ACLY level." (PMID 36309693, 2022).
diabetes (10 papers, 2018 to 2024). "ACLY is not only involved in cancer cell signaling pathway, but also participates in the metabolism process of diabetes." (PMID 31088900, 2019). "Moreover, the pharmacological inhibition of ACLY successfully reversed delayed wound healing in a murine model of diabetes." (PMID 38654733, 2024). "Inhibition of ACLY reverses delayed wound healing in a murine model of diabetes." (PMID 38654733, 2024). "Increased ACLY activity in the brain of diabetes might be related to lipid accumulation in the brain." (PMID 31675964, 2019). "Increased levels of citrate, acetyl CoA, and lactate in the brain of streptozotocin-induced diabetic rats may support the role of ACLY to produce lactate in the brain in diabetes because of ACLY cleaves citrate into acetyl CoA and OAA." (PMID 31675964, 2019). "Overall, ACLY in islet plays a key part in the molecular level of type 2 diabetes and maybe a potential target for diabetes." (PMID 31088900, 2019).
melanoma (10 papers, 2019 to 2025). A malignant, usually aggressive tumor composed of atypical, neoplastic melanocytes. "Moreover, increased ACLY expression was associated with poor outcome of patients with melanoma." (PMID 33121001, 2020). "The expression of branched-chain amino acid transaminase 2 (BCAT2) also affects the levels of FASN and ACLY, promoting De Novo lipogenesis and facilitating melanoma progression." (PMID 38921444, 2024). "Recently, the enzyme BCKDHA, known as branched-chain keto acid dehydrogenase E1 subunit alpha, which is involved in branched-chain amino acid metabolism, has been found to regulate the expression of FASN and ATP-citrate lyase (ACLY) in melanoma." (PMID 38921444, 2024). "Of note, the activation of lipid-producing enzymes such as ACLY and SREBP1 also causes drug resistance of melanoma toward targeted therapy." (PMID 36003368, 2022). "Accordingly, ACLY expression, the critical rate-limiting enzyme in lipogenesis, is significantly increased in melanoma as an oncogenic factor." (PMID 36224606, 2022). "Most of the enzymes associated with fatty acid synthesis (e.g., FASN, SCD, ACC, ACLY), and receptors related to lipid uptake (e.g., FAT/CD36, FATPs, and FABPpm) are upregulated in several cancers, including melanoma." (PMID 35406721, 2022). "Moreover, melanoma cells upregulate ATP-citrate lyase (ACLY) and sterol regulatory element-binding proteins (SREBPs) to activate de novo lipogenesis." (PMID 40539068, 2025). "In addition to intaking more exogenous lipids, de novo lipogenesis is activated in melanoma cells through upregulating the enzymes controlling lipid synthesis—ATP-citrate lyase (ACLY) and sterol regulatory element-binding protein (SREBP), for instance." (PMID 36003368, 2022). "The ACLY lipid synthesis enzyme activates the P300 acetyltransferase, leading to histone acetylation at the microphthalmia-associated transcription factor (MITF) locus and increased transcription of the MITF-PGC1α axis, promoting melanoma progression and resistance to MAPK inhibitors." (PMID 40539068, 2025). "Therefore, the combination of MAPK and ACLY can be efficient in melanoma treatment." (PMID 36224606, 2022). "A recent study in melanoma shows that BCAT-IN-2 leads to fewer colonies forming in vitro and reduces aberrant FASN and ACLY expression." (PMID 40507232, 2025). "To further validate the clinical relevance of our findings, we analyzed a tissue microarray (TMA) comprising 111 tumor samples from melanoma patients to assess the expression of SLC25A1, ACLY, and FSP1 using multiplex immunofluorescence (mIF) staining." (PMID 39881208, 2025). "In melanoma, increased BCAA metabolism leads to higher expression of FASN and ACLY genes, suggesting higher de novo lipogenesis." (PMID 40507232, 2025). "This conversion is catalyzed by ATP citrate lyase (ACLY), which is overexpressed in a variety of cancer types, including melanoma." (PMID 33121001, 2020). "ACLY induces the resistance to MAPK inhibition by activating acetyltransferase P300 to acetylate the histone at the MITF locus, thus promoting the transcription of the MITF-PGC1 α axis and ultimately facilitating melanoma growth." (PMID 36003368, 2022). "Four DNFA enzymes – SCD, FASN, ACLY and ACSS2 – exhibit the highest levels of mRNA expression in skin cutaneous melanoma (SKCM) compared to other tumor types, whereas expression of ACACA is less elevated in melanomas." (PMID 31316083, 2019).
nasopharyngeal carcinoma (10 papers, 2021 to 2025). A carcinoma arising from the nasopharyngeal epithelium. "The lncRNA TINCR is overexpressed in nasopharyngeal carcinoma and interacts with ATP citrate lyase (ACLY), an enzyme that metabolizes citrate to acetyl-CoA." (PMID 40804479, 2025). "ERP44 promotes progression in nasopharyngeal carcinoma via its interaction with ATP citrate lyase and regulation of epithelial-mesenchymal transition (EMT)." (PMID 35707371, 2022). "ACLY expression is known to contribute to the upregulated fatty acid biosynthesis and glycolysis and play a role in the radio-resistance of nasopharyngeal carcinoma." (PMID 36591481, 2022). "In nasopharyngeal carcinoma, the interaction between ERP44 and ACLY promotes the malignant phenotype of nasopharyngeal carcinoma cells." (PMID 36059811, 2022). "In nasopharyngeal carcinoma cells, the lncRNA TINCR interacts directly with ACLY, thereby preserving ACLY protein stability by impeding its ubiquitination-mediated degradation." (PMID 39551780, 2024). "A novel lipid metabolic related lncRNA, TINCR, was identified to be significantly overexpressed in nasopharyngeal carcinoma (NPC), and can promote proliferation, metastasis and cisplatin resistance of NPC by affecting ACLY‐mediated de novo lipid biosynthesis." (PMID 37939296, 2024).
cervical carcinoma (9 papers, 2016 to 2024). A carcinoma arising from either the exocervical squamous epithelium or the endocervical glandular epithelium. "As one of key enzyme in Acetyl-CoA biosynthesis, ACLY is associated with various malignancies, such as colorectal, gastric, and cervical cancers." (PMID 37122003, 2023). "In addition, higher ACLY expression levels in cancer patients were associated with shorter disease relapse free survivals (RFS) in lung, liver, bladder, and cervical cancers." (PMID 34747157, 2022). "We conclude that, in cervical carcinoma HTB-34 cells, CA modestly activates AMPK, while Met exerts its effect on FA biosynthesis by downregulation of several enzymes involved in the de novo synthesis of long unsaturated FA, such as ACLY, FAS, ELOVL6, and SCD1." (PMID 28230778, 2017).
gastric adenocarcinoma (9 papers, 2019 to 2022). "While ACLY expression is associated with advanced stage and prognosis in gastric adenocarcinoma, MAOA expression can promote the proliferation and metastasis of human gastric tumor cells by inducing mitochondrial dysfunction and aerobic glycolysis." (PMID 36090054, 2022). "In gastric adenocarcinoma, high ACLY expression level was associated with the advanced stage and poor prognosis." (PMID 33593371, 2021). "ACLY can serve as a biomarker for predicting disease progression and prognosis in patients with gastric adenocarcinoma." (PMID 35785165, 2022). "In the context of fatty acid synthesis, the enzyme ATP citrate lyase (ACLY – responsible for the conversion of citrate to oxaloacetate and cytosolic acetyl-CoA) has been associated with metastatic disease in gastric adenocarcinoma (GA)." (PMID 31922096, 2019). "High ACLY expression level is also connected with lymph node metastasis and advanced stages in gastric adenocarcinoma." (PMID 31511060, 2019). "High ACLY protein level was correlated with advanced stages and lymph node metastasis in gastric adenocarcinoma." (PMID 31511060, 2019). "ACLY is often highly expressed in gastric adenocarcinoma patients." (PMID 35785165, 2022). "ATP citrate lyase (ACLY), which is involved in the transformation of citrate to oxaloacetate, showed overexpression in gastric adenocarcinoma patients." (PMID 35178126, 2022).
lung adenocarcinoma (9 papers, 2018 to 2025). A carcinoma that arises from the lung and is characterized by the presence of malignant glandular epithelial cells. "Phosphorylated ACLY expression in human lung adenocarcinoma is implicated with stage, differentiation and poor prognosis." (PMID 33393219, 2021). "In human lung adenocarcinoma, phosphorylated ACLY, which is directly regulated by the phosphoinositide 3-kinase (PI3K)-AKT pathway, contributes to ACLY protein stabilization." (PMID 39551780, 2024). "Overexpression of ACLY correlates with poor outcomes of human cancers such as lung adenocarcinoma and acute myeloid leukemia." (PMID 37122003, 2023). "Since elevated levels of ACLY have been reported in lung adenocarcinoma, we next examined the levels of ACLY and caspase-10 in different grades of lung adenocarcinoma." (PMID 31534141, 2019). "The expression levels of phospho-Akt and phospho-ACLY are positively correlated, and ACLY is directly activated by the PI3K-Akt pathway in lung adenocarcinoma cell lines." (PMID 30410721, 2018). "Theexpression and activity of ACLY are significantly upregulated in severalmalignancies such as bladder, breast, lung, liver, stomach, prostate, and coloncancers (25, 29, –, 33), and the overexpression of ACLY correlateswith poor prognosis in lung adenocarcinoma and blood cancers." (PMID 39475274, 2024). "We observed that consistent with increase in ACLY levels, GCN5-targeted H3K9 acetylation levels were also upregulated with increasing grades of lung adenocarcinoma as compared to matched normal adjacent tissue." (PMID 31534141, 2019). "Moreover, Kaplan–Meier survival analysis indicated that patients with high SLC25A1 and ACLY expression in skin cutaneous melanoma (SKCM) and lung adenocarcinoma (LUAD) had shorter survival than those with low SLC25A1 and ACLY expression." (PMID 39881208, 2025). "The expression of ACLY in human lung adenocarcinoma has been investigated to be higher compared with non-carcinogenic lung control tissue and contributes to increased lipogenesis and tumor growth." (PMID 35203617, 2022). "Activated ACLY is a negative prognostic factor in human lung adenocarcinomas." (PMID 30410721, 2018).
glioma (8 papers, 2014 to 2025). A benign or malignant brain and spinal cord tumor that arises from glial cells (astrocytes, oligodendrocytes, ependymal cells). "It has recently been shown that FABP7 translocates to the nucleus and interacts with nuclear factors (e.g., ACLY, RXRα) to modulate gene expression associated with cellular physiology and metabolism in both astrocytes and glioma cells." (PMID 39596296, 2024). "Emerging evidence implicates palmitoylation in regulating nutrient transporters (e.g., GLUT1) and metabolic enzymes (e.g., ACLY), suggesting its potential role in rewiring glioma metabolism—a dimension meriting dedicated metabolomic studies." (PMID 40535771, 2025). "ZBTB4 bind to the HK2 and ACLY promoter regions and inhibit their transcription, thereby impairing glycolipid metabolism and proliferation of glioma cells." (PMID 34047477, 2021). "The GEPIA from The Cancer Genome Atlas and GTEx consortiums also indicate significant ACLY upregulation in glioma." (PMID 32812201, 2020). "Furthermore, FABP7 was recently found to interact with nuclear factors, such as ACLY and RXRα, to regulate gene expression in astrocytes and glioma cells, influencing cellular metabolism and proliferation." (PMID 39596296, 2024). "Interestingly, the glioma exosomes contained ATP-citrate synthase (ACLY), which converts citric acid into acetyl coenzyme A, and fatty acid synthase (FASN), which synthesizes palmitate from acetyl coenzyme A in the presence of NADPH." (PMID 32708613, 2020). "The levels of ACLY/pACLY modulate tumourigenicity in gliomas." (PMID 25277207, 2014). "We recently reported that FABP7 in astrocytes interacts with ATP citrate lyase in the nucleus, participating in histone acetylation and that FABP7 binding to oleic acid (OA) in glioma cells modulates histone acetylation." (PMID 40017805, 2025).
Insulin resistance (7 papers, 2011 to 2025). Increased resistance towards insulin, that is, diminished effectiveness of insulin in reducing blood glucose levels. "EA improves insulin resistance in hyperuricemic rats by activating C1q/tumor necrosis factor-associated protein-3 and inhibiting ATP citrate lyase, thereby increasing glucose metabolism." (PMID 38915316, 2024). "However, the naturally occurring ACLY inhibitor, hydroxycitrate, has properties of a calorie-restriction mimetic, and can reduce adiposity and insulin resistance in obese Zucker rats." (PMID 40636718, 2025). "Liver insulin resistance is confirmed by the impaired phosphorylation of Akt at both residues, Thr308 and Ser473, as well as the impaired phosphorylation of ACLY at Ser455, a downstream target of Akt." (PMID 36810903, 2023). "Importantly, insulin resistance may contribute to the functional activation of ACLY, as elevated levels of glucose-6-phosphate and fructose-6-phosphate—common in hyperglycemic states—are known allosteric activators of ACLY." (PMID 41220581, 2025). "Furthermore, an abnormal citrate/isocitrate ratio can activate cytosolic ATP-citrate lyase (ACLY), whose expression is inversely correlated with the degree of insulin resistance." (PMID 41480360, 2025).